C3 (complement C3)
Diseases named in the same sentence as C3 in open-access papers (continued):
Sharing a sentence is not in itself a finding about the gene and the disease.
cancer (continued). "In addition, cancer-cell-intrinsic inflammatory tumor subclusters also showed an upregulation of C1R (log2FC = 0.86), C1S (log2FC = 0.46), and C3 (log2FC = 0.48), while the corresponding macrophages showed an upregulation of C1q genes (C1QA, C1QB, C1QC)." (PMID 36973268, 2023). "These DEGs were not only enriched in biochemical processes related to the regulation of lymphocyte activation and cytokine receptor interaction pathways but also GSEA showed that C3 was likely to be involved in cancer-related pathways explaining the worse prognosis of C3." (PMID 37122696, 2023). "If a cancer patient carries mutations of C3 genes, the complete restoration of IO matching would not be possible." (PMID 37269056, 2023). "The complement system (C3) plays a key role in cancer progression aside from boosting immunity." (PMID 37759310, 2023). "In the TME of ccRCC, TAMs produce C1q, whereas cancer cells synthetize C1r, C1s, C4, and C3." (PMID 38003705, 2023). "Inflammatory responses (C3) have the best survival prognosis, and we found that a greater abundance of C3-linked immune mycotypes was associated with better overall survival (OS) across 20 cancer types (middle and right) without sequencing center associations." (PMID 36179670, 2022). "In addition, overexpression of complement 3 (C3) has recently been reported to reduce the expression of E-cadherin that induces the EMT phenomenon, whereas C3 knockdown increases the expression of E-cadherin in cancer tissues." (PMID 36018840, 2022). "It is worth mentioning that targeting the receptor C5aR rather than the components C3 or C5, allows opsonization to take place in order to protect cancer patients from the risk of acquiring bacterial infections." (PMID 35173724, 2022). "In addition, deletion of C3 in cancer cells has been shown to enhance the efficacy of anti-PD-L1 treatment." (PMID 35755033, 2022). "Studies indicate that some oncogenic proteins regulate the infiltration of immune cells into tumors; however, our correlation analysis revealed that the expression levels of C3, C3AR1, and C5AR1 were strongly associated with the infiltration of immune cells into tumors across the TCGA cancer types." (PMID 34439277, 2021). "In addition, complement C3 gene expression was also increased in the presence of carnosine, and although C3 is generally known to promote cancer cell growth, there are studies showing a dual role of complement in cancer and its anti-cancer effects." (PMID 33809496, 2021). "The study indicated not only the abnormal presence of C3, factor B, and clustering in prostate fluids from cancer patients but also a previously unknown C-terminal C3 cleavage product." (PMID 34572075, 2021). "The C3- and C5-derived fragments C3a and C5a participate in the establishment of a chronic inflammatory state that may favor tumorigenesis and cancer progression." (PMID 34359708, 2021). "A high level of C3 has been observed in many cancer patients` serum." (PMID 34620162, 2021). "We found that C3, C5, C3AR1, and C5AR1 expression is negatively associated with infiltrations of M2-TAMs and MDSCs but positively associated with CAF infiltrations in various cancer types." (PMID 34439277, 2021). "C3 deficiency did not affect the cancer response to 7,12-dimethylbenz[a]anthracene treatment alone but reduced the epidermal hyperplasia during 12-O-tetradecanoylphorbol-13-acetate–induced inflammation." (PMID 32682912, 2021). "We found that the complements C3, C5, C3AR1, and C5AR1 have deregulated expression in human malignancies and are associated with activation of immune-related oncogenic processes and poor prognosis of cancer patients." (PMID 34439277, 2021). "C3 activates the C3a receptor in the choroid plexus epithelium to disrupt the blood‐CSF barrier, allowing plasma amphiregulin and other mitogens to enter the CSF and promote cancer cell growth." (PMID 33377642, 2020).
cancer (continued). "Thus, by suppressing C3 deposition on the cancer cells, CD46 and CD55 can lower, on one hand, the extent of MAC generation and CDC, and on the other hand, reduce immune protection through complement-dependent cellular cytotoxicity." (PMID 31024572, 2019). "Moreover, a number of studies reported that patients with cancer (including OC) produce altered levels of complement C3 as compared with healthy subjects." (PMID 28683725, 2017). "Cancer-associated fibroblasts (CAF) isolated from mouse lungs bearing early-stage breast cancer metastasis 24 h after the last doxorubicin dose, showed significant upregulation of complement genes across the complement pathway, including C1ra, C1s, C2, C3, C4a, C5, C7 and C8a." (PMID 39765018, 2025). "However, the biological mechanisms of the interactions between TNXB-SDC4, THY1-(ITGAX+ITGB2), ICAM1-(ITGAX+ITGB2), and C3-(ITGAX+ITGB2) ligand-receptor pairs in cancer remain unclear and warrant further investigation." (PMID 37954130, 2023). "In addition, most of the C3 signals were localized in LMSCs, which were marked by Nestin, suggesting that C3 may also be produced by LMSCs in cancer patients." (PMID 34707103, 2021). "In addition, further gene set mining suggested that higher C3 expression could promote cancer proliferation, invasion, and adhesion." (PMID 34722636, 2021). "Moreover, treatment targeting immune components, such as MBL or the complement C3 cascade, may prove to be effective in the therapeutic armamentarium against cancer." (PMID 34202433, 2021). "Besides, we observed another cancer-specific modification (Ac-K283), which induces a drastic conformational change in C3 molecule, according to the molecular dynamic simulation, but keeps the C3-factor stable, which probably reflects the acquisition of new activities and functional properties." (PMID 34588485, 2021). "On the other hand, intracellular activation of C3 by cathepsin proteinases and C3-independent activation of C5 by urokinase indicate, that complement-independent activation of the complement system may play a role in progression cSCC and other cancers." (PMID 31331124, 2019). "In the cancer microenvironment, these secreted inhibitors may contribute to protection of cancer cells from complement attack by blocking complement activation at the C1 and C3 activation steps." (PMID 31024572, 2019). "Because C3 inhibited growth pathways in several different assays, we decided to investigate whether C3 could inhibit wound healing in a scratch test assay as a measure of cancer cell aggressiveness as it relates to their migration capacity." (PMID 29464047, 2018). "In this study, cancer cells were incubated with MBL, MASPs, and complement C3 for complement activation, and the supernatant was collected to treat murine platelets." (PMID 40492591, 2025). "Higher gene expression of C3, a central factor in complement system activation, may potentially mediate inflammation, leukocyte adhesion and migration, all of which are relevant to muscle responses and align with previous studies that reported activation of the complement system in cancer." (PMID 41243421, 2025). "Cancer cells were incubated with MBL, MASPs, and complement 3 (C3) protein to trigger complement activation." (PMID 40492591, 2025). "These cancer cells express high levels of Her2 and of the complement regulator CD55, preventing C3 cleavage by the C3 convertase." (PMID 40370471, 2025). "They recognized a significant expression of C3 and classical pathway components (C1QA, C1QB, C1QC, C1R, C1S, C4A, and C2) in all cancer types." (PMID 38003705, 2023). "These include: CDH1, MUC1, THBS4, and MSLN for PEs related to cancer; ADA2, CXCL10, and WARS for TB-PEs; CRP, S100A9, and VIM for parapneumonic PEs; and C9, LDHA, HPX, LDHB, and C3 for benign-PEs." (PMID 35197508, 2022). "The complement components C3, C5, C3AR1, and C5AR1 serve as attractive targets for strategizing cancer immunotherapy and response follow-up." (PMID 34439277, 2021).
cancer (continued). "In conclusion, the complement components C3, C5, C3AR1, and C5AR1 serve as attractive targets for strategizing cancer immunotherapy and response follow-up." (PMID 34439277, 2021). "Collectively, C3, C5, C3AR1, and C5AR1 demonstrated context-dependent expression in and a prognostic impact on various cancer types." (PMID 34439277, 2021). "Complement C3 with other components of the classical pathway, such as C1QA, C1QB, C1QC, C1R, C1S, C4A, and C2 are found expressed in several cancer cell types." (PMID 34572075, 2021). "We used the differential gene expression module of TIMER to evaluate the differential expression of C3, C5, C3AR1, and C5AR1 between human cancer and normal tissues across the TCGA database." (PMID 34439277, 2021). "More biological evidence is required to further understand the role of the complement components C3, C5, C3AR1, and C5AR1 in cancer progression." (PMID 34439277, 2021). "We assessed the correlation of C3, C5, C3AR1, and C5AR1 expression with infiltrations of six types of immune cells across the TCGA cancer types." (PMID 34439277, 2021). "We employed CR1 to block exogenous activation of C3 and detected a weakened expression of p-STAT3 and IL-6 compared with AG490-treated cancer cells." (PMID 31928530, 2020). "As anticipated, AGI-134 induced the deposition of complement C3b/C3bi and led to the formation of the membrane attack complex (MAC) C5b-C9 on A549 cancer cells." (PMID 31889898, 2019). "Such C3 marker upregulation is concordant with our previous observations of cancer cell-induced plasticity of C1 cultures, whereby C1 cultures treated with CM from TGFβ1-/2-secreting PC3 cells significantly upregulated C3/myofibroblast markers in a manner dependent on fibroblast TGFβR activity." (PMID 41327318, 2025). "C3 and its active fragment C3a, downstream effectors of classical complement activation mediated by C1q/C1s/C1r, were time‐dependently increased following AZD4573 treatment, as well as PD‐L1 in KRAS‐mutant cancer cells." (PMID 39254172, 2024). "PML, C3, TXN, KRT6C, F2, PTK2, TNF, which could enable HIF-mediated inflammatory response during cancer development." (PMID 36845724, 2023). "Thus, we further examined these genes and found that the mRNA expressions of C3, C5, CFB, and CLU were correlated with cancer stage and prognosis in patients with HCC." (PMID 34813686, 2022). "Collectively, our study demonstrates that the complement component proteins C3, C5, C3AR1, and C5AR1 are candidate biomarkers for cancer diagnosis, prognosis, and therapy outcomes, and thus serve as attractive targets for strategizing cancer immunotherapy and the response follow-up." (PMID 34439277, 2021). "In the context of cancer, C3(H2O) has not been evaluated, although, notably, dysregulation of the alternative pathway of complement activation, which can be initiated by C3(H2O), has been demonstrated in several hematological cancers." (PMID 33147799, 2020). "CD46, a membrane-bound complement regulatory protein able to interact with C3 activation fragments and found at high levels in some cancer types, has also been proposed as a negative regulator of immune recognition." (PMID 31031765, 2019). "Finally, we discovered eight genes (MME, SOX17, AGTR1, PGR, ESR1, PAX8, C3 and IRF6) with high amplification frequency compared to other genes across the cancer types." (PMID 31879572, 2019). "However, since complement activation can be initiated by three pathways, and each converges on C3, our studies do not distinguish which of these pathway(s) are involved in cancer cachexia." (PMID 40198138, 2025). "Moreover, we found increased C3 secretion in malignant ascites in patients with high BMI, reinforcing the idea that adipose tissue–derived factors play an important role in shaping the TME and modulating cancer cell behavior." (PMID 39964754, 2025).
cancer (continued). "For example, ADT levels of EPCAM on cancer/epithelial cells (c0, c4, c8, c14 and c15), CD31 (PECAM1) and CD34 on endothelial cells (c7 and c9), CD146 (MCAM) on perivascular cells (c11), CD90 (THY1) and CD34 on CAFs (c13) and CD45 (PTPRC) on immune cells (c3, c5 and c12)." (PMID 33971952, 2021). "However, only C3 expression was significantly higher in cachectic cancer patients compared to non-cachectic ones." (PMID 33142864, 2020). "However, only the C3 expression was significantly higher (p < 0.05) in cachectic cancer patients compared to non-cachectic ones." (PMID 33142864, 2020). "To date, the cancer-specific C3 index has not been widely adopted in cancer populations, as such it remains unknown whether this might provide a more accurate adjustment for comorbidity in cancer survival analysis research." (PMID 31189947, 2019). "In addition, both CFB and C3 have not been previously reported to be related to cancer biomarkers, according to the IPA biomarker analysis and The Human Protein Atlas." (PMID 26540631, 2015). "Baseline plasma C3 was quantified in 4552 participants, without previous hospital admission due to CKD, from the Malmö Diet and Cancer cohort study." (PMID 30791918, 2019). "The role of complement C3 in the crosstalk between FAO and cancer immunity was never reported." (PMID 33633112, 2021). "In addition, we found some up-regulated genes, ADRA2C, C3, and C5AR1, which were not previously reported in cancer stemness." (PMID 30420637, 2018). "We compared serum levels of complement components (C3, C4, C1q), activation products (C3a, C4a, C5a, Ba, Bb, sC5b-9), and regulators (Factor I, Factor H) between patients who developed irMyositis or irNeuropathy, ICI-treated cancer patients without irAEs, and healthy controls." (PMID 40506552, 2025).
renal disease (128 papers, 2009 to 2026). "Humanizing C3 in mice triggered C3 glomerulopathy (C3G), a complement-mediated kidney disease, because of impaired regulation of human C3 by mouse inhibitors, causing spontaneous complement activation." (PMID 40519165, 2025). "Still in humans, inactivation or deficiency of complement C3 can lead to recurring bacterial infections and renal disease." (PMID 39813225, 2025). "Only 2.3% of the assessments had active renal disease (grade A or B), which was shown to have the strongest association with low C3/C4 and elevated anti-dsDNA." (PMID 36284526, 2022). "The variation in the concentration of the complement molecules has been associated with an increase in the risk of retinopathy, nephropathy, and diabetic neuropathy, especially high levels of C3." (PMID 35955802, 2022). "It has been shown that complement synthesis is closely associated with the development and progression of renal disease and that C3 secreted by macrophages leads to IL-17A-mediated inflammatory cell infiltration in renal tissue." (PMID 34424825, 2021). "In our patient cohort, low C3 levels were associated with more severe renal disease (as evidenced by high serum creatinine and need for hemodialysis) and worse renal prognosis (progression to ESRD)." (PMID 32787590, 2020). "There are conflicting literature data regarding the potential association between C3 levels and severity of renal disease." (PMID 32787590, 2020). "Almost one of four patients with AAV has low C3 levels at diagnosis which is associated with more severe renal disease and worse renal outcomes (ESRD)." (PMID 32787590, 2020). "In many kidney diseases, altered circulating C3 levels, renal C3 deposits, and genetic mutations in C3 can be observed." (PMID 30791918, 2019). "Progressive renal disease in Cfh–/– mice is associated with accumulation of C3 activation fragments including iC3b along the GBM." (PMID 26924054, 2016). "As anti-ficolin-3, anti-C1q, anti-dsDNA and low complement C3 and/or C4 were associated with renal disease activity, we characterized the diagnostic performances of these biomarkers, alone or in combination, in our cohort." (PMID 27631981, 2016). "However, there are few kidney diseases in which decreased serum complement components (C3 or C4) can be used as diagnostic biomarkers or as indicators of disease progression." (PMID 40283082, 2025). "Because excessive activation of C3-derived molecules and their associating molecules is causal for several renal diseases, their inhibitors, such as a C3-targeting peptide and a factor B-blocking compound, have been developed and are currently under clinical evaluation." (PMID 33971198, 2021). "Genetic deficiencies or abnormalities of FH lead to uncontrolled C3 activation and the accumulation of C3 and C5 activation products within the renal glomerulus and cause the rare renal diseases C3 glomerulopathy (C3G) and atypical hemolytic uremic syndrome (aHUS)." (PMID 34112227, 2021). "Local C3 synthesis in the kidney has been linked to the progression of renal diseases." (PMID 32481551, 2020). "Future studies could evaluate the in vivo interactions between THP and the complement system using crosses of THP and C3 knockout mice with wildtype mice and evaluating their susceptibility to complement mediated renal disease models such as IRI." (PMID 28742158, 2017). "To highlight complement C3 expression in injured proximal tubular epithelial cells across different kidney disease states, we analyzed the KPMP datasets." (PMID 40519169, 2025). "The pattern suggests that C3 is activated in response to injury and remains elevated during maladaptive repair, implicating it in the progression of kidney disease." (PMID 40519169, 2025). "Complement C3 (C3) plays an important role in the immune system and is also involved in kidney diseases." (PMID 39857298, 2025).